DPP4 (dipeptidyl peptidase 4)
Diseases named in the same sentence as DPP4 in open-access papers (continued):
Sharing a sentence is not in itself a finding about the gene and the disease.
endothelial dysfunction (continued). "This study may increase the understanding of the pathways that contribute to which DPP-4 inhibitor attenuates endothelial dysfunction." (PMID 29951533, 2018). "This can be a random finding due to the small number of events, but it may also represent possible additional effects of DPP4 inhibition, such as the effect on endothelial dysfunction and inflammation." (PMID 23537430, 2013). "The study hypothesizes that DPP4 may exert a substantial role in endothelial dysfunction." (PMID 37615707, 2024). "Moreover, sDPP4 might contribute to endothelial dysfunction as it has been shown that DPP4 impaired the endothelium-dependent relaxation elicited by acetylcholine in a concentration-dependent manner." (PMID 36009573, 2022). "Both, DPP-4 inhibition and the GLP-1 analog improved hypotension and endothelial dysfunction in endotoxemic rats." (PMID 34439423, 2021). "The positive effects included histologic changes, endothelial dysfunction and oxidative stress through stabilization of RAS by a DPP-4 inhibitor." (PMID 32489704, 2020). "However, the effects of other DPP-4 inhibitors on postprandial lipemia-induced endothelial dysfunction have not been fully evaluated." (PMID 23298374, 2013).
viral infection (35 papers, 2017 to 2025). "In our study, therapy with DPP-4 inhibitors prior to virus infection was associated with a lower risk of death [OR = 0.59 (95% CI: 0.57–0.61), p < 0.001]." (PMID 36017317, 2022). "Interaction between MERS-CoV S protein and DPP4 was essential for viral infection and correlated with susceptibility to MERS-CoV infection, as well as with viral genome detection in the culture medium of infected cells." (PMID 36009573, 2022). "Notably, the interaction between MERS-CoV spike protein and DPP4 is essential for viral infection and is correlated with susceptibility to MERS-CoV infection, as well as with viral genome detection in the culture medium of infected cells." (PMID 37896834, 2023). "Similarly, a controlled study depended on the database of the World Health Organization (WHO) also implicates the use of DPP-4 inhibitors in increasing the risk of different viral infections." (PMID 36180664, 2022). "Authors propose that high serum DPP4 levels could protect from viral infection by competitively inhibiting the virus binding to cellular DPP4, whereas low serum DPP4 levels could increase the risk of infection." (PMID 36009573, 2022). "In addition, immunomodulatory effects of DPP-4 inhibitors may reduce exaggeration of the immune response in viral infections; thereby decreasing the risk of immune-mediated tissue injury as in Covid-19." (PMID 36180664, 2022). "Compound EC50 values on pseudotyped SARS-CoV-1, SARS-CoV-2 viral infection in ACE2-expressing HEK293 cells or on pseudotyped MERS viral entry in DPP4-expressing HELA cells." (PMID 40443526, 2025). "Differences in glycosylation patterns of mouse DPP4 restrict viral infection, whereas DPP4 receptors from bats, camels, and humans can support efficient viral infection." (PMID 41050696, 2025). "Collectively, these data suggest that the KDM6A-KMT2D-p300 axis specifically regulates ACE2 and DPP4 expression and virus infection in primary human cells." (PMID 37410700, 2023). "To explore the correlation between DPP4 expression and viral infection, we selected a variety of gene markers involved throughout viral processes." (PMID 37351182, 2023). "Regarding the role played by DPP4 with respect to virus infection, literature data are quite conflicting." (PMID 35406799, 2022). "Further, high levels of the cell surface protein dipeptidyl peptidase-4 (DPP4) have a protective effect against viral infections." (PMID 35769263, 2022). "Accordingly, ADA competed with MERS-CoV for binding to DPP4, acting as a virus–DPP4 attachment inhibitor and preventing virus infection." (PMID 36009573, 2022). "The RBD of MERS-CoV binds to human dipeptidyl peptidase 4 (hDPP4) (cellular receptor) and gains entry into the target cell for viral infection." (PMID 30988390, 2019). "The anti-DPP4 (CD26) antibodies such as 1F7, 2F9, and YS110 prevent the entry of MERS-CoV into susceptible cells, obstructing the virus infection." (PMID 30984127, 2019). "Consistent with HBECs, A485 treatment inhibited ACE2 and DPP4 expression and viral infection." (PMID 37410700, 2023). "Finally, by using the basic reproductive ratio R0 = Nβλλ1/cdγ, let us give some simple discussions on the interactions between the protein DPP4 and the virus infection." (PMID 28894474, 2017). "In addition, DPP4 in the oral of elderly was significantly down regulated, which may be related to viral infection and oral microbiome dysbiosis." (PMID 37351182, 2023). "Except for the expression of DPP4 in the jejunum and ileum of young pigs, the expression pattern of the selected coronavirus receptors was very different and not correlated with the age-dependent susceptibility to viral infections." (PMID 37055856, 2023). "DPP4 may be related to viral infection and dysbiosis of the oral microbiome in elderly individuals." (PMID 37351182, 2023). "However, further studies are required to establish the critical role of DPP-4 in viral infections." (PMID 34451848, 2021).
viral infection (continued). "In support of this, CRISPR‒Cas9-mediated knockout of DPP4 in N2a (N2aDPP4KO) cells led to a sharp reduction in PHEV entry and reproduction, while overexpression of DPP4 in N2aDPP4KO cells rescued viral infection." (PMID 38829136, 2024). "Limited reports suggest that membrane-bound DPP-4 may interact with the SARS-CoV-2 spike glycoprotein, and thus may propagate viral infection." (PMID 37064327, 2023). "Likewise, while ACE2 levels are very low in cortical cells, a high DPP4 expression was found in cortical astrocytes infected with SARS-CoV-2, and interestingly, DPP4 inhibition reduced viral infection." (PMID 36009573, 2022). "We also show that IL22 reduces the expression of viral entry receptors (e.g. ACE2, TMPRSS2, DPP4, CD46 and TNFRSF14), increases the expression of anti-viral proteins (e.g. RSAD2, AOS, ISG20 and Mx1) and, consequently, reduces the viral infection of neighboring cells." (PMID 34045640, 2021). "The targeting of the DPP4 protein itself may be valuable for the development of vaccines for MERS and other viral infections." (PMID 34955820, 2021). "This is consistent with other reports that A549 cells lack DPP4, the putative receptor for MERS-CoV, and are therefore not susceptible to productive viral infection." (PMID 30781790, 2019). "Moreover, cells that supported MERS-CoV replication showed significantly higher DPP4 mRNA expression than those that were non-susceptible to MERS-CoV, suggesting that cellular DPP4 expression is critical for viral infection." (PMID 30531999, 2018). "In contrast, α-cell-specific transcripts including GCG, ARX, BAMBI, DPP4, and POU6F2 were not affected by infection, which corresponded with our observation that viral infection was infrequent in α cells." (PMID 32093375, 2020). "While both ANPEP and DPP4 are already known as a target receptors for other coronaviruses (human coronavirus 229E, swine epidemic diarrhea virus, canine coronavirus, feline coronavirus, for ANPEP and MERS-CoV for DPP4), the relationship between ENPEP and viral infection is not yet known." (PMID 32759645, 2020).
Cognitive impairment (34 papers, 2015 to 2026). Abnormal cognition is characterized by deficits in thinking, reasoning, or remembering. "Firstly a retrospective study demonstrated that two years of DPP-4 inhibitor use was associated with reduced cognitive decline in diabetic patients with mild cognitive impairment (MCI)." (PMID 41480353, 2025). "In previous studies, increased activity of dipeptidyl peptidase-4 inhibitors (DPP4) was independently associated with mild cognitive impairment (MCI) in elderly patients with T2D." (PMID 38379936, 2024). "Moreover, neurodegenerative disorders and cognitive impairment have been associated with elevated DPP-4 levels." (PMID 41528544, 2026). "Supporting this hypothesis, DPP4 inhibition reduced cognitive impairments associated with neurodegenerative and metabolic disorders." (PMID 40490517, 2025). "The present work thus suggests DPP-4 inhibitors may be suitable in the management of T2DM patients at risk of cognitive impairment, as a result of its beneficial effects on cerebral perfusion and cognitive function." (PMID 31126115, 2019). "However, other studies have suggested that DPP4 inhibitors may be associated with an increased risk of cognitive impairment in T2D patients." (PMID 38379936, 2024). "Our study shows that even short-term treatment with dipeptidyl peptidase 4 inhibitors can significantly slow the progress of cognitive impairment in mice, indicating the potential therapeutic value of this type of disorder." (PMID 38860903, 2025). "(2024) investigated the effects of the DPP-4 inhibitor linagliptin on mild cognitive impairment in mice, focusing on the regulation of microglia." (PMID 41480353, 2025). "The results of another retrospective study also showed that DPP4 inhibitors were protective against cognitive impairment compared with metformin." (PMID 38379936, 2024). "All of these suggest that DPP4 inhibitors have a positive effect on cognitive impairment in T2D and have a potential role in preventing cognitive impairment." (PMID 38379936, 2024). "In individuals with T2DM and MCI, those that received a DPP4 inhibitor were protected against worsening cognitive impairment." (PMID 39518747, 2024). "This figure indicates that DPP4 inhibitors effectively reduce fasting blood glucose and thus effectively improve cognitive impairment in diabetic patients." (PMID 38379936, 2024). "In our meta-analysis, DPP4 inhibitors showed an improved effect on cognitive impairment in T2D, and DPP4i has previously been shown to have an improved effect on cognitive impairment." (PMID 38379936, 2024). "Sitagliptin, as a DPP-4 inhibitor, prolongs the activity of natural GLP-1 and enhances Aβ degradation, potentially exerting a beneficial effect in alleviating cognitive impairment associated with Alzheimer’s disease." (PMID 38002034, 2023). "These substrates were either activated or inactivated by DPP-4 to partially modulate related signalling pathways involving inflammation or oxidative stress, thus facilitating cognitive impairment in diabetic conditions." (PMID 38082288, 2023). "An upregulation of DPP-4 expression had been suggested to be related to cognitive impairment via an overload of mitochondrial calcium, while cognitive impairment was alleviated after downregulation of DPP-4 expression." (PMID 38082288, 2023). "Linagliptin, a dipeptidyl peptidase-4 inhibitor, mitigates cognitive deficits and pathology in the 3xTg-AD mouse model of AD." (PMID 34108878, 2021). "The purpose of this study is to explore the effect of the DPP-4 inhibitor on cognitive impairment in diabetic patients by meta-analysis." (PMID 32756077, 2020). "The present manuscript want to provide the protocol that will be used in the systematic review and meta-analysis to evaluate the role of DPP-4 inhibitors in cognitive impairment of T2DM patients and analyze the mechanism as much as possible." (PMID 32756077, 2020).
Cognitive impairment (continued). "More interestingly, animal studies have proved that DPP4 activity inhibitors ameliorated cognitive impairment through suppressing inflammatory reaction, oxidative stress, or GLP-1 degradation." (PMID 28798686, 2017). "DPP-4 inhibition with linagliptin counteracted cognitive impairment and brain atrophy induced by transient cerebral ischemia in diabetic mice, independently of blood glucose lowering effect." (PMID 25986579, 2015). "The data suggest that DPP4 inhibitors can improve cognitive impairment in patients." (PMID 38379936, 2024). "According to previous studies, brain-derived neurotrophic factor (BDNF) decreases and DPP4 activity increases in the peripheral circulation of mild cognitive impairment, and the negative correlation is caused by oxidative stress and inflammation." (PMID 38379936, 2024). "We hypothesized that the high heterogeneity of the effects of DPP4 inhibitors on cognitive impairment was due to other factors such as country, age, sex, and duration of treatment." (PMID 38379936, 2024). "Some research reports that DPP-4 inhibitors may have a significant role in neurodegenerative and cognitive disorders." (PMID 38002034, 2023). "Furthermore, enhanced DPP-4 activity increased oxidative stress and activated inflammatory response, partially contributing to cognitive impairment in T2DM." (PMID 38082288, 2023). "Experimental evidence also supports the use of dipeptidyl peptidase-4 inhibitors or gliptins as potential drugs to prevent cognitive impairment through the preservation of Glucagon-like peptide 1 (GLP-1) function and increasing neurogenesis, among many other mechanisms." (PMID 34072230, 2021). "Previous researches suggested that decreased BDNF and increased DPP4 activities were found in the periphery circulation of patients with MCI, suggesting that BDNF and DPP4 activity might both play a pathogenetic role in the development of cognitive impairment." (PMID 30886577, 2019). "In rodents, DPP-4 inhibitors reduce neuronal loss and cognitive impairment in ischemic stroke, an effect which is independent of the hypoglycemic action of DPP-4." (PMID 30186247, 2018). "The present study was undertaken to test our hypothesis that linagliptin, a DPP-4 inhibitor, administration following transient cerebral ischemia can ameliorate cognitive impairment and brain injury in diabetic mice." (PMID 25986579, 2015). "Additionally, DPP4 inhibitors may protect against the progression of cognitive disorders in diabetic individuals by increasing neurotrophin levels, such as BDNF, NGF, and NT-4, promoting neuronal growth, survival, and synaptic plasticity." (PMID 38860903, 2025). "In addition to the slightly higher mean sMMSE score, the considerably higher BDNF levels of the patients on DPP-4 inhibitor treatment suggest that the DPP-4 inhibitors may have protective effects against cognitive impairment." (PMID 38510866, 2024). "When evaluating the effect of DPP4 inhibitors on cognitive impairment in T2D, we selected the Montreal Score (MoCA) or the MMSE as an indicator to improve cognitive impairment." (PMID 38379936, 2024). "The results of the target-component network analysis showed that ADRB2, ADRA1B, DPP4, ACHE and ADRA1D played a key role in the treatment of mild cognitive impairment." (PMID 35646138, 2022). "Targeting neuroinflammation with alogliptin, a dipeptidyl peptidase-4 inhibitor, has shown neuroprotective effects by targeting the TLR4/MYD88/NF-κB signaling cascade against lipopolysaccharide (LPS)-induced neuroinflammation and cognitive impairment in mice." (PMID 40801649, 2025). "DPP4 (CD26) bound to the insulin‐like growth factor 2‐receptor on Treg cells, impairing Tregs function, polarizing microglia toward a pro‐inflammatory phenotype in the hippocampus, and ultimately leading to neuroinflammation and cognitive impairment in T2DM." (PMID 40296350, 2025).
Cognitive impairment (continued). "In addition, common anti-diabetic treatments such as dipeptidyl peptidase-4 (DPP4) inhibitors, glucagon-like peptide-1 (GLP-1) agonists and metformin have shown promise in the treatment of PD and cognitive impairment in human and animal models of PD." (PMID 34393754, 2021). "In this study, we showed that the DPP-4 inhibitor, linagliptin, improved cognitive impairment, reduced oxidative stress, and suppressed microglial activation in streptozotocin (STZ)-induced diabetic mice, which could evaluate the effect of DPP-4 inhibitor independently of glucose-lowering." (PMID 32032367, 2020).
liver fibrosis (34 papers, 2010 to 2025). "Another molecule that has been implicated in liver fibrosis resolution is DPP-4/CD26, whose increased circulating activity is inversely correlated with a drastic reduction in Kupffer cell population upon liver injury." (PMID 32823659, 2020). "DPP4 also plays a role in the degradation of extracellular matrix, the imbalance of which is a hallmark of liver fibrosis." (PMID 30824564, 2019). "Thus, we examined if systemic and hepatic loss of Dpp4 in mice affected liver fibrosis." (PMID 36472923, 2023). "Another finding from this study is that switching from existing OHAs, primarily DPP-4 inhibitors, which are also incretin-related drugs, was also effective at improving liver fibrosis." (PMID 39861190, 2025). "DPP4 inhibitors have a protective role in models of hepatic fibrosis and renal fibrosis, which implies that DPP4 is pro-fibrotic and promotes CKD in SNx obese rats." (PMID 37571269, 2023). "Gardenoside can ameliorate lipid deposition and liver fibrosis, and has been shown to decrease the expression levels of dipeptidyl peptidase-4 (DPP4), CCCTC-binding factor (CTCF), NLRP3, ASC, caspase-1 p20, GSDMD-N, and IL-1β in vitro and in vivo NAFLD models." (PMID 36016562, 2022). "DPP4 has been identified as a multifunctional glycoprotein involved in different biological processes, including inflammation, liver fibrosis, malignant transformation, and tumor immunity." (PMID 32245205, 2020). "Based on these findings, several DPP-4 inhibitors (i.e., sitagliptin and alogliptin) have been reported to exert direct inhibitory effects on liver fibrosis development." (PMID 31561561, 2019). "We have recently demonstrated that a dipeptidyl peptidase-4 (DPP-4) inhibitor successfully attenuated liver fibrosis." (PMID 31561561, 2019). "Collectively, TGR5 agonist and DPP-4 inhibitor appears to be a novel strategy against liver fibrosis under diabetic conditions." (PMID 31561561, 2019). "DPP-4 plays a role in fibroblast activation in the liver by activating hepatic stellate cells, while sitagliptin, a DPP-4 inhibitor, attenuates hepatic fibrosis by suppressing activated hepatic stellate cells in rats." (PMID 26191473, 2015). "In the present study, we firstly found the significant amelioration of liver fibrosis was accompanied with the decrement of DPP4 hepatic gene expression and plasma DPP4 concentrations when treated with betaine." (PMID 26491462, 2015). "Depressing renal and hepatic fibrosis has been found to occur with DPP4 inhibitors." (PMID 40429343, 2025). "What’s more, it has been shown that neuropeptide (NPY) is upregulated in human MASLD and that B cells may require dipeptidyl peptidase 4 (DPP4) to contribute to CCL4-induced hepatic fibrosis via NPY to induce maximal collagen production (Wang XM." (PMID 40761743, 2025). "Interestingly, hepatocyte‐specific silencing of dipeptidyl peptidase 4 (DPP4) prevents liver fibrosis and adipose tissue inflammation; however, how this affects the heart remains to be investigated." (PMID 40771104, 2025). "Soluble, circulating DPP4 has been shown to be a marker of liver fibrosis." (PMID 36472923, 2023). "While DPP4 has not been reported to be an interferon-stimulated gene, its level of expression has been previously associated with liver fibrosis." (PMID 26181438, 2015). "Overall, these data suggest that systemic, not hepatic, loss of Dpp4 increases liver fibrosis." (PMID 36472923, 2023). "Systemic, not hepatic, loss of Dpp4 in aged mice increases hepatic fibrosis." (PMID 36472923, 2023). "Finally, our study is the first one which investigated DPP4 activity and concentration in relation to the FIB-4 score, a broadly validated marker of liver fibrosis which play a central role in the diagnostic algorithm of NAFLD and NASH in high risk populations." (PMID 32852705, 2021).